SMARCA4 (SWI/SNF related BAF chromatin remodeling complex subunit ATPase 4)
Diseases named in the same sentence as SMARCA4 in open-access papers (continued):
Sharing a sentence is not in itself a finding about the gene and the disease.
non-small cell lung carcinoma (continued). "However, patients with non-small cell lung cancer (NSCLC) caused by SMARCA4 deletion have a worse prognosis than those with normal SMARCA4 expression." (PMID 39697230, 2024). "Immunohistochemical staining confirmed SMARCA4-deficient non-small cell lung cancer." (PMID 39465834, 2024). "Firstly, as a single case report of a patient with SMARCA4-deficient non-small cell lung cancer (NSCLC) with concurrent EGFR exon 21 L858R mutation, the findings may not be broadly generalizable." (PMID 39465834, 2024). "Approximately 5% of conventional non-small cell lung cancers (NSCLCs) are deficient in SMARCA4." (PMID 38542211, 2024). "This case shows the efficacy of nivolumab to treat SMARCA4-deficient non-small cell lung carcinoma." (PMID 37051241, 2023). "SMARCA4-deficient non-small cell carcinoma is an aggressive neoplasm with poor outcome." (PMID 37051241, 2023). "Notably, SMARCA4 mutations were slightly more common than ARID1A mutations in cases of non-small cell lung cancer, cervical cancer, and melanoma." (PMID 36371186, 2022). "SMARCA4-deficient non-small cell lung cancer (SMARCA4-dNSCLC) is a rare primary lung malignancy." (PMID 36002194, 2022). "SMARCA4 is frequently mutated in multiple cancer types, including non-small cell lung carcinoma (NSCLC) (10–35%), Burkitt’s lymphoma (15%) and childhood medulloblastoma (5–10%), and occasionally mutated in pancreatic adenocarcinoma, ovarian clear cell carcinoma and melanoma." (PMID 34315468, 2021). "Herein, we discuss the pathophysiology of SMARCA4, the clinicopathological consequences, and different detection methods, highlighting the perspectives and challenges in the assessment of SMARCA4 deficiency for the management of non-small cell lung cancer patients." (PMID 34440689, 2021). "However, the latest WHO classification of thoracic tumors has separated this entity into SMARCA4-deficient undifferentiated thoracic tumors (DUT) and SMARCA4-deficient non-small cell lung carcinoma (SMARCA4-dNSCLC)." (PMID 34440689, 2021). "Additionally, inactivating somatic mutations in SMARCA4 have been reported in many cancer cell lines, including non-small cell lung cancer and small cell carcinoma of the ovary." (PMID 32337068, 2020). "Non-small cell lung cancers with inactivating SMARCA4 mutations are currently undruggable." (PMID 30718506, 2019). "SMARCA4-deficient tumors represent a heterogeneous group of malignancies, including thoracic SMARCA4-deficient undifferentiated tumors, SMARCA4-mutated non-small cell lung cancer (non-small cell lung carcinoma), and undifferentiated carcinomas involving the gastrointestinal and gynecologic tracts." (PMID 40867304, 2025). "Pathologically, it can be distinguished from SMARCA4-deficient non-small cell lung cancer (SMARCA4-dNSCLC) based on histological morphology and immunohistochemistry, yet whether there are differences in their clinical features, sensitivity to radiotherapy, and prognosis remains unknown." (PMID 41777060, 2025). "Mutations in SMARCA4 have been shown to co-exist with KRAS mutations but are mutually exclusive from common targetable non-small cell lung carcinoma (NSCLC) oncogenes, including EGFR, ALK, MET, ROS-1, and RET." (PMID 40406754, 2025). "SMARCA4-deficient non-small cell lung cancer (NSCLC) is an uncommon primary malignant epithelial tumor originating in the lung, classified as a distinct clinicopathologic entity in the World Health Organization Classification of Thoracic Tumors, published in May 2021." (PMID 39465834, 2024). "Interestingly, EZH2 inhibition had varying effects in a preclinical study of non-small cell lung cancers, with increased sensitization to topoisomerase II inhibitors in the tumor subset demonstrating BRG1/SMARCA4 loss-of-function mutations or EGFR gain-of-function mutations." (PMID 29093822, 2017).
non-small cell lung carcinoma (continued). "More importantly, we conducted an in-depth analysis of the TCR diversity index as a reflection of the immune microenvironment, highlighting its therapeutic prognostic potential in SMARCA4 non-small cell lung cancer." (PMID 41142791, 2025). "The pathological diagnosis confirmed non-small cell carcinoma in the left lower lobe basal segment, consistent with SMARCA4-DNSCLC based on morphology and immunohistochemistry." (PMID 41395620, 2025). "This tumor with poor prognosis is easily confused with SMARCA4-deficent non-small cell lung cancer or sarcoma." (PMID 38347129, 2024). "SMARCA2 has become an appealing synthetic-lethal therapeutic target for various cancers, including non-small cell lung cancer (NSCLC), as mutational loss of SMARCA4 in many cancers leads to a functional dependency on residual SMARCA2 activity 22–25." (PMID 38755248, 2024). "Attempts to target SMARCA4 in various types of tumors, including non-small-cell lung cancer and brain tumors, have been reported in the preclinical phase." (PMID 38610978, 2024). "As for SMARCA4, in non-small cell lung cancer, SMARCA4 deletion is sensitive to combination of etoposide and DZNep (EZH2 inhibitor)." (PMID 38427070, 2024). "Further research is needed to unravel the intricate interplay between SMARCA4, chromatin remodeling, and tumorigenesis in non-small cell lung cancer." (PMID 39063938, 2024). "A549-LN cells were derived from the A549 human non-small cell lung cancer line which has increased sensitivity to oxidative phosphorylation inhibition due to a mutation of the SWI/SNF chromatin remodelling complex member, SMARCA-4." (PMID 37679822, 2023). "On the other hand, the SMARCA4 alteration rate is 2.7-10% in common carcinomas of the lung such as adenocarcinoma, small cell carcinoma, squamous cell carcinoma, non-small cell carcinoma, and large cell neuroendocrine carcinoma." (PMID 36178285, 2023). "Although little is known about the efficacy of ICIs for SMARCA4-alterated cancers, some case reports for patients with relapsed SCCOHT, SMARCA4-deficient thoracic sarcoma and SMACA4-altered non-small cell lung cancer have been published." (PMID 35163487, 2022). "Expression of SMARCA4 is silent in 15% up to 50% of human non-small-cell lung cancer (NSCLC) tissues." (PMID 36361605, 2022). "Somatic mutations in SMARCA4 and/or BRG1 (Brahma-related gene 1) loss are present in a subset of non-small cell lung carcinomas with distinct morphological features, harboring less EGFR mutations, but more KRAS, STK11, and KEAP1 mutations." (PMID 36371186, 2022). "Here, we show that this vulnerability is conserved in non-small cell lung cancer (NSCLC), where SMARCA4 loss also results in reduced cyclin D1 expression and selective sensitivity to CDK4/6 inhibitors." (PMID 30718506, 2019). "In Small Cell Carcinoma of the Ovary, Hypercalcaemic Type (SCCOHT) and Non-Small Cell Lung Cancer cell cells, SMARCA4 and SMARCA2 acted as tumor suppressors." (PMID 28445125, 2017). "Core subunits of the BAF complex, SMARCA4 (encoding BRG1) and SMARCA2 (encoding BRM), are highly homologous, with mutations or deletions closely associated with various tumors, including 10% of non-small cell lung cancers." (PMID 40661782, 2025). "SMARCA4 mutation rates were reported to account for approximately 8% of non-small cell lung cancers, but not all mutations resulted in loss of SMARCA4 expression." (PMID 38710944, 2025). "A loss of both SMARCA4 and SMARCA2 has been found in 10–26% of non-small cell carcinomas." (PMID 36178285, 2023). "Furthermore, ICI treatment correlated with significantly improved overall outcomes in SMARCA4-aberrant non-small cell lung cancer." (PMID 35163487, 2022). "We saw a significant decrease in cell viability in SMARCB1 deficient cell lines as compared to urothelial carcinoma cell line, JMSU1 (SWI/SNF wild type), or non-small cell lung cancer cell line, A549 (SMARCA4 mutant) (two-tailed t-test p-values 4.5e-5 and 4.6e-5)." (PMID 30860482, 2019).
non-small cell lung carcinoma (continued). "SMARCA4, a well-known tumor suppressor gene that can serve as prognostic indicators in non-small cell lung cancer and breast cancer, was under-expressed in a small fraction of samples from the Shedden_2008 study, and the corresponding patients had worse survival outcome." (PMID 30532070, 2019). "In 2014, SMARCA4 was identified to be one of tumour suppressor gene in the non-small cell lung cancer because inactivation of SMARCA4 could promote cancer aggressiveness by altering chromatin organization." (PMID 26859295, 2016). "Deficiency in the SMARCA4 subunit has been described in rare malignant neoplasms with poor prognosis, such as small cell carcinoma of the ovary, hypercalcemia type (SCCOHT), some thoracic carcinomas, gastrointestinal and genitourinary tract carcinomas, and non-small-cell lung carcinoma." (PMID 39590317, 2024). "Moreover, immunostaining of SMARCA4 disappears even in non-small cell lung cancer." (PMID 35151345, 2022). "A carcinoid subtype in which SMARCA4, KRAS, FGF3/4/19, STK11, CDKN2A/B, and other genomic alterations predominate in non-small cell lung cancer-like subtypes." (PMID 40661782, 2025). "In addition, this tumor frequently displays the robust expression of one or more stem cell markers, such as SOX2, CD34, and SALL4, which can facilitate the differential diagnosis of SMARCA4-deficient non-small cell lung cancer (NSCLC) (SMARCA4-dNSCLC), typically negative for these markers." (PMID 38881888, 2024). "Genomic studies have identified frequent mutations in subunits of the SWI/SNF chromatin remodeling complex including SMARCA4 and ARID1A in non-small cell lung cancer." (PMID 39345502, 2024). "In this report, we describe a male non-smoker diagnosed with SMARCA4-deficient, EML4-ALK non-small cell lung cancer who has been undergoing ensartinib targeted therapy for 3 months, resulting in a significant partial response." (PMID 40416876, 2025). "This method has been successfully demonstrated to supress the growth of non-small cell lung cancer lacking SMARCA4 in vitro and in vivo through xenograft mouse models." (PMID 37433987, 2023).
small cell carcinoma of the ovary (88 papers, 2014 to 2026). "Small Cell Carcinoma of the Ovary (SCCO) is an extremely rare form of ovarian cancer characterised by bi-allelic mutations in the SMARCA4 gene, a member of the SWI/SNF chromatin remodelling complex." (PMID 41988129, 2026). "Small cell carcinoma of the ovary, hypercalcemic type—a rare malignancy of the female reproductive system—currently represents the prototype of SMARCA4-deficient neoplasms, as SMARCA4 loss is found in all cases." (PMID 39888726, 2025). "This alteration was also identified in her familial lineage, including her sister who was previously diagnosed with small cell carcinoma of the ovary, hypercalcemic type, a malignancy highly associated with SMARCA4 mutations." (PMID 39439958, 2024). "Particularly, SMARCA4 variants, including both germline (43%) and somatic (57%) mutations, have been implicated as causative genetic alterations in small cell carcinoma of the ovary, hypercalcemic type (SCCOHT)." (PMID 39439958, 2024). "Inactivating mutations in SMARCA4 are characteristic of small cell carcinoma of the ovary, hypercalcaemic type (SCCOHT) and can also occur in malignant rhabdoid tumors." (PMID 38180245, 2024). "SMARCA4, a gene associated with the small cell carcinoma of the ovary, hypercalcemic type (SCCOHT), appears to be the sole ovarian cancer (OC) predisposition gene associated with a very early age at diagnosis (≤40 years)." (PMID 37345881, 2023). "Small cell carcinoma of the ovary, hypercalcaemic type, is a rare and extremely aggressive subtype of ovarian cancer associated with somatic and germline deleterious variants of SMARCA4." (PMID 37258796, 2023). "Germline and somatic alterations in the SMARCA4 gene and loss of BRG1 protein expression have been established as defining events in small cell carcinoma of the ovary, hypercalcemic type (SCCOHT)." (PMID 38090508, 2023). "SMARCA4 acts as a tumor suppressor in hypercalcemic small cell carcinoma of the ovary, and its deficiency has been reported to be involved in carcinogenesis." (PMID 37626774, 2023). "Most of the Small Cell Carcinoma of the Ovary Hypercalcemic Type (SCCOHT) patients carried variants in SMARCA4." (PMID 36180906, 2022). "Female carriers of pathogenic germline mutations of SMARCA4 are at risk of an aggressive type of undifferentiated ovarian cancer called small cell carcinoma of the ovary, hypercalcemic type (SCCOHT)." (PMID 33907931, 2021). "Pathogenic variants in the SMARCA4 gene are increasingly associated with small-cell carcinoma of the ovary, hypercalcemic type, or adenocarcinomas of the lung and endometrium." (PMID 34680878, 2021). "SMARCA4 loss leads to extremely aggressive malignancy in young patients, such as ovarian small cell carcinomas of the hypercalcemic type and thoracic sarcoma." (PMID 32972432, 2020). "In small-cell carcinomas of the ovary, hypercalcemic type (SCCOHTs), characterized by bi-allelic inactivating mutations of SMARCA4, loss of SMARCA2 expression is frequently observed." (PMID 31406271, 2019). "SMARCA4 is frequently (over 90%) mutated in ovarian small cell carcinomas of the hypercalcemic type, however, to our knowledge, the first case of a germline SMARCA4 mutation in a patient with HGSOC was recently reported." (PMID 30200265, 2018). "SMARCA4 mutations have recently been identified as driving lesions of the ovarian small cell carcinoma of hypercalcemic type (SCCHT)." (PMID 25886974, 2015). "SMARCA4 gene alterations have recently been found to underlie a development of the ovarian small cell carcinoma of hypercalcemic type." (PMID 25886974, 2015). "Recent reports also revealed that small cell carcinoma of the ovary, hypercalcemic type, displays frequent inactivating germline and somatic mutations in SMARCA4, and this mutation is very rare in other common tumors." (PMID 25042800, 2014).
small cell carcinoma of the ovary (continued). "It shares morphological, molecular, and clinical features with other SMARCA4-deficient neoplasms, such as SMARCA4-deficient thoracic sarcoma and small cell carcinoma of the ovary, hypercalcemic type (SCCOHT), suggesting a spectrum of related tumors linked to SWI/SNF complex dysfunction." (PMID 41463261, 2025). "From a molecular perspective, accumulating evidence indicates that ovarian small-cell carcinomas, particularly the hypercalcemic type, almost universally carry deleterious SMARCA4 mutations, leading to their reclassification as malignant rhabdoid tumors within the same pathological spectrum." (PMID 41293259, 2025). "Moreover, paraneoplastic hypercalcemia, while being specifically associated with the ETV6::NTRK3 fusions, is also significantly associated with SMARCA4 inactivation in the majority of small cell carcinoma of the ovary, hypercalcemic type." (PMID 36690805, 2023). "Additionally, SMARCA4 variants were identified in three patients with small cell carcinoma of the ovary, hypercalcemic type, accounting for 0.3% of our ovarian cancer patient cohort." (PMID 35971132, 2022). "Approximately half of ovarian clear cell carcinomas (OCCC) carry mutations in the SWI/SNF subunit ARID1A, while small cell carcinoma of the ovary hypercalcemic type (SCCOHT) presents with inactivating mutations of the SWI/SNF ATPase SMARCA4 alongside epigenetic silencing of the ATPase SMARCA2." (PMID 32649682, 2020). "Moreover, ARID3A and SMARCA4, recently found to be mutated in small cell carcinoma of the ovary, are both located on the short arm of chromosome 19, which is recurrently deleted in 29/80 and 18/80 SS genomes, respectively." (PMID 26415585, 2015). "In addition to the ten selected OC predisposition genes, germline PVs causing a loss of SMARCA4 gene function predispose for the rare small cell carcinoma of the ovary, hypercalcemic type (SCCOHT), primarily affecting females under 40 years with an average age of onset of 24–30 years." (PMID 37345881, 2023). "Small cell carcinoma of the ovary-hypercalcemic type (SCCOHT) is a rare ovarian cancer affecting young females and is driven by the loss of both SWI/SNF ATPases SMARCA4 and SMARCA2." (PMID 39906560, 2025). "Small-cell carcinoma of the ovary, hypercalcemic type (SCCOHT) is a rare and highly aggressive ovarian malignancy associated with SMARCA4 mutations." (PMID 41431072, 2025). "Small-cell carcinoma of the ovary, hypercalcemic type (SCCOHT) is an extremely rare and aggressive ovarian malignancy associated with SMARCA4 mutation, accounting for less than 0.01% of ovarian tumors." (PMID 41431072, 2025). "Small cell carcinomas of the ovary hypercalcemic type (SCCOHT) is characterized by SMARCA4 alterations, and exhibits good response to immunotherapy." (PMID 38225273, 2024). "Small cell carcinoma of the ovary, hypercalcemic type (SCCOHT) is a rare form of aggressive ovarian malignancy linked with mutations in the SMARCA4 gene." (PMID 38455342, 2024). "ICIs have shown promise as a therapeutic approach in SMARCA-altered cancers such as SMARCA4-deficient thoracic sarcoma, SMARCA4-altered non-small-cell lung cancer (NSCLC), and small cell carcinoma of the ovary, hypercalcemic type (SCCOHT)." (PMID 39199375, 2024). "EpS showed the highest EA (p < 0.01) across all three DNAm clocks compared to those generated from SMARCA4-deficient ATRT, SMARCA4-deficient MRT, and small cell carcinoma of the ovary, hypercalcemic type (SCCOHT) (supplementary 7)." (PMID 38879847, 2024). "SMARCA4-UT exhibits morphological features similar to the malignant rhabdoid tumor (MRT), small cell carcinoma of the ovary of the hypercalcemic type (SCCOHT), and INI1-deficient tumor, but SMARCA4-UT differs from SCCOHT and MRT from a genomic perspective." (PMID 37115343, 2023).